MYC (MYC proto-oncogene, bHLH transcription factor)
Diseases named in the same sentence as MYC in open-access papers (continued):
Sharing a sentence is not in itself a finding about the gene and the disease.
tumor (continued). "An in vitro study confirmed that MYCMI-6 could suppress c-MYC-dependent cell growth, which correlates with the level of c-MYC expression in tumour cells." (PMID 35267559, 2022). "Of the three patients (43%) with SD after two cycles, one patient whose tumour was co-amplified for c-MYC and HER2 went on to achieve disease control for 32 weeks after nine cycles of treatment with a partial metabolic response in the primary tumour on serial PET–CT scans." (PMID 35448150, 2022). "Lastly, let-7c—a tumor suppressor miRNA— was shown to negatively regulate c-Myc, while CCAT1 is able to derepress c-Myc expression by sponging let-7c, thus creating a positive feedback loop to promote CSE-induced CCAT1 and MYC expression." (PMID 35892574, 2022). "Previous studies have shown that MYC overexpression throughout development can drive HCC formation, but an expression of MYC by hydrodynamic tail vein injection in C57BL6 only results in tumours in combination with other oncogenic drivers." (PMID 36433941, 2022). "MYC-related genes play an important role in tumor transformation, but not all transformed cases have an increased MYC signature." (PMID 35565286, 2022). "Also, signatures reflecting oncogenic signalling such as MYC, KRAS, PI3K/mTOR and Notch, were enriched in the tumours of the young." (PMID 35995935, 2022). "Strikingly, we obtained mid/hindbrain progenitor cells as most similar embryonic cell type for ATRT-SHH tumor cells, whereas primordial germ cells (PGCs) emerged as the cell type with the highest similarity score for ATRT-MYC (MYC IC-RT and MYC spinal tumors) and eRT." (PMID 35318328, 2022). "There was no dataset on tumor types with a significantly higher expression of MYC mRNA in the ERI2 mRNA high-expressing group." (PMID 35887071, 2022). "PVT1B suppresses MYC transcription in cis, thereby inhibiting MYC-dependent cellular proliferation and tumor growth but not malignant progression in a mouse model of lung carcinogenesis." (PMID 36366537, 2022). "In all three tumor models, MYCMI-7 treatment led to reduced MYC or MYCN expression in tumor tissue." (PMID 36874405, 2022). "A high uptake of glucose in normal brain and orthotopic xenografts compared to in vitro cell cultures was found, suggesting that MYC-amplified MB use glucose as carbon source for the glutamate synthesis (deriving by TCA intermediates), depending on the tumor environmental conditions." (PMID 36340043, 2022). "In other words, MYC signaling leads to increased expression of CD47 and PD-L1 in tumor cells." (PMID 37305016, 2022). "However, in relation to cancer, a relevant observation on MYC is that MYC-driven tumorigenesis requires sumoylation, since downregulation of SUMO E1 is lethal for tumor cells overexpressing MYC." (PMID 35887358, 2022). "As PRMT5 in tumor cells inhibited PD-L1 expression, GSK3326595 (PRMT5 inhibitor) and anti-PD-1 combination therapy was more effective than either treatment alone in murine xenograft liver tumors, a MYC-driven spontaneous HCC model, and murine melanoma models." (PMID 35493527, 2022). "In both groups, IDC-P and the adjacent invasive carcinoma arose from the same clone, leaving no information about the original tumour focus, and MYC amplifications were found with high frequencies." (PMID 35159086, 2022). "Due to the discrepancy between the activities of MYC S146L in MCF10A cells and colon organoids, we hypothesized that the tumor promoting function of MYC S146L is context-dependent and only beneficial following the acquisition of other oncogenic alterations." (PMID 36018850, 2022). "Our studies demonstrate that expression of MUC1-C in classic NE SCLC-A, variant NE SCLC-N, and non-NE SCLC-P cells activates the MYC pathway, which is dysregulated in SCLC cells and promotes tumor progression, drug resistance, and poor clinical outcomes." (PMID 35612556, 2022).
tumor (continued). "Since differentiated myofibers can sustain high levels of oncogene expression without tumor formation, we suggest that MYC in muscle fibers induced by loading is a core component of rapid yet functional adaptive remodeling." (PMID 36150502, 2022). "The tumor also showed BRCA2 isoform switching and a MYC amplification." (PMID 36344544, 2022). "The molecular etiology of EC and the pathogenic role of the demonstrated here overexpression of MYC, NR5A2, SNAI1, and TWIST1 in tumor-adjacent tissues is not clear." (PMID 36140779, 2022). "Interestingly, it was suggested by some previous researchers in their studies that in the tumor microenvironment, FOXP3 reduces glycolysis in Tregs by inhibiting MYC, and it in turn allows them to be free from lactate limitation." (PMID 35454171, 2022). "In our IDHwt LGG samples, we showed that decreased PLCG1 expression suppressed tumor proliferation, migration and invasion and promoted apoptosis owing to a disturbance of the essential functions of PLCG1, such as protein secretion, MYC targets, mitotic spindle, the G2/M checkpoint, and E2F targets." (PMID 34697421, 2022). "Omomyc has been shown to have a potent anti-proliferative effect with sustained tumour regression with no detrimental effect on healthy tissue, thus for the first time, c-MYC inhibition can be considered as a feasible therapeutic anti-cancer strategy." (PMID 35267559, 2022). "Also, PIK3CA overtook MYC as the top CNA-based oncogene, and PTEN displaced CDKN2A from the top CNA-based tumour suppressor spot." (PMID 35975235, 2022). "FBXW7 reshapes the proliferative niches of tumor cells through ubiquitinating and degrading several crucial signal molecules, such as c-MYC, c-Jun, phosphatidylinositol 3-kinase (PI3K)/AKT, mTOR, Notch, as well as JAK/STAT signaling pathway." (PMID 35515121, 2022). "As a typical tumor suppressor, PDCD4 (programed cell death 4) promotes cell apoptosis and inhibits cell cycle through blocking the PI3K/AKT pathway, ultimately affecting the downstream genes, such as cyclinD1 and c-MYC." (PMID 36230970, 2022). "Moreover, JQ1 and VS-6063 (an inhibitor of the focal adhesion kinase (FAK))-mediated co-inhibition of BRD4/MYC and FAK cooperatively induced apoptosis in TNBC cells and reduced in vivo tumour growth in the TNBC syngeneic model 4T1." (PMID 35267409, 2022). "Since the pro-proliferation effect of polyamines can increase the oxygen consumption of cells, whether the regulation of HIF1α expression by MYC is related to the upregulation of ODC by MYC and thus increases oxygen consumption by tumor cells." (PMID 35912204, 2022). "The c-MYC gene leads to increased expression of PD-L1 and CD47 at the surface of tumor cells." (PMID 37305016, 2022). "SIRT1 increases MYC transcriptional activity through deacetylation, which in turn increases NAD+ through increased expression of NAMPT, thereby enhancing SIRT1 activity, and this positive feedback inhibits tumor cell senescence and apoptosis." (PMID 36523971, 2022). "We hypothesize that solid tumor formation in vivo may lead to various microenvironmental conditions, including hypoxia, that may reactivate essential stemness genes such as MYC and HIF1A to reprogram tumor cells into stem-like cells." (PMID 35404029, 2022). "One patient with a dual c-MYC and HER2 highly co-amplified tumour continued treatment for 32 weeks which may hint at enhanced efficacy of ibrutinib in a co-amplified tumour; however, most patients progressed after 2 cycles (57%)." (PMID 35448150, 2022). "In addition, another study found that in MYC-driven breast cancer, DF2 induced apoptosis in human triple-negative breast cancer (TNBC) cell lines and hindered the growth of xenografted tumor in vivo." (PMID 35351856, 2022). "Tumor subsets express NK cell receptors, CD95/CD95L, CD30, MYC, and PDL1." (PMID 35054466, 2022).
tumor (continued). "Interestingly, many pathways and cell types that were enriched in PM when compared to primary tumours are also features of CMS4 CRC (e.g.: high TGFβ, angiogenesis, complement, stromal fibroblasts, monocytes, macrophages; low WNT and MYC target genes)." (PMID 35194192, 2022). "In addition, Ganetespib and 17-AAG decreased PD-L1 transcription through destabilizing Hsp90 clients MYC and STAT3 in monocytes and tumor cells at the sub-cytotoxic concentration, and Ganetespib diminished PD-L1 level on MC38 tumor cells in vivo." (PMID 36341371, 2022). "MYC expression was detected in the tumors while mice were fed doxycycline (MYC-ON) and MYC is no longer detectable in the tumor within 3 days of removing doxycycline from the diet (MYC-OFF)." (PMID 35760778, 2022). "Moreover, YAP was enriched at the promoter regions of several key factors involved in the stemness of tumor cells, such as SOX9, SMAD2/4, OLIG2, and MYC." (PMID 35322024, 2022). "Further analysis of patients with available molecular subgroup showed 33 (73.3%) males and 12 (26.7%) females, one patient with residual tumor ≥ 1.5cm2, 39 (86.7%) classic (CMB), 4 large-cell/anaplastic (LCAMB) and 2 desmoplastic (DMB) histology, 2 MYC and 4 MYCN amplified cases." (PMID 35190934, 2022). "Whereas tumor growth rates were not significantly altered upon tamoxifen-induced MycERT2 translocation in already established tumors, MYC activation resulted in depletion of immune infiltrates." (PMID 36323660, 2022). "We, therefore, hypothesized that miR-378a was a potential tumor suppressor by repressing ODC1 and c-MYC expression." (PMID 36457036, 2022). "Importantly, in a subcutaneous mouse model of MYC-driven MB, we have confirmed that OTX015 or panobinostat alone suppresses MB tumor growth, and the combination of these synergistically blocks MB progression." (PMID 36357906, 2022). "This patient’s tumor may represent another means (e.g., NUTM1 fusion) by which MYC overexpression compels oncogenesis in the neoplastic thyrocyte." (PMID 34997561, 2022). "It is known that KRAS can initiate tumor progression and formation of early-stage PanIN, whereas the absence of functional MYC prevents transition to PDAC." (PMID 34947972, 2021). "Several oncogenes, like MYC, SRC, and VEGF, harbor complex structures in their 5′UTR, such as G-quadruplexes structures or IRES elements, enhancing their translation in specific situations like tumor development." (PMID 33078202, 2021). "Interestingly, a number of studies have found that hypoxia plays a role in the induction of tumor cell growth and metastasis by PI3K/Akt signaling and MYC target V1 signaling." (PMID 34637697, 2021). "As indicated by western blot analysis, expression of LOX-1, c-MYC, and SULT2B1 in tumor tissues of nude mice was lowered by knocking down OLR1, whilst SULT2B1 expression in tumor tissues of nude mice was markedly strengthened by oe-SULT2B1 treatment in the presence of sh-OLR1As." (PMID 34921134, 2021). "The results showed that upregulation of circACTN4 could increase the expressions of MYC, CDK4, CCND2 and Ki67 in tumor tissues, whereas circACTN4 silencing reduced the expression levels of these proteins." (PMID 34116677, 2021).
tumor (continued). "It is therefore conceivable that our EPN lines, enriched in stem-like cells, express a high MYCN/MYC ratio, that is switched by differentiation, similarly to what may occur in EPN specimens, where SCs represent only a restricted population of the tumor burden." (PMID 33668642, 2021). "Using tissue-specific regulatory RNAs rather than MYC gene mRNA as targets provides a potential opportunity to selectively influence c-Myc expression in cells of a particular tumor type." (PMID 34440124, 2021). "In agreement with our hypothesis, we found a low MYCN/MYC mRNA ratio in EPN specimens, where SCs represent a restricted population of the tumor burden." (PMID 33668642, 2021). "We previously reported that the MYC protein was undetectable in E1-MYC cell secretion and exosomes and that the exosomes were similar before and after MYC transformation, demonstrating that MSC exosomes do not carry MYC oncoprotein to promote tumor growth." (PMID 33918628, 2021). "The improved T cell-stimulatory capacity of λ-MYC TIDCs detected in vitro, which was also seen in an HPV16 tumor model after anti-PD1/anti-CTLA-4 treatment, may be due to the altered cytokine expression pattern, but other mechanisms cannot be precluded." (PMID 33141285, 2021). "In addition to E2F, several transcription factors with critical involvement in carcinogenesis and tumor progression control EZH2 transcription, such as MYC, NF-YA, STAT3, ETS, and ELK1." (PMID 34943970, 2021). "Together, these data supported the hypothesis that DUSP9 exerts a tumor suppressive role in HCC by inactivating the ERK pathway and lowering the level of the ERK targets MYC and Cyclin D1." (PMID 34768967, 2021). "Similar to MYC, NSUN2 was also highly expressed in various tumours." (PMID 34638933, 2021). "The MYC gene expression dataset and clinical information of 515 LUAD patients were downloaded from The Cancer Genome Atlas (TCGA) database, 59 of whom had paracancer tissues corresponding to their tumor sites." (PMID 33540574, 2021). "For example the levels of MYC are often elevated in tumours relative to non-cancerous tissue of the same origin." (PMID 33799592, 2021). "Another study demonstrated that tumor progression and dissemination in Vκ*MYC is not under exclusive control of the TME." (PMID 34149703, 2021). "It is known that c-MYC can participate in the process of tumor initiation, but it has not yet been discovered if it is involved in tumor progression or the response to therapy." (PMID 34204834, 2021). "In the undiluted tumor samples not more than 75 K on-target reads were needed to robustly detect the MYC, BCL2, and BCL6 rearrangements." (PMID 34099699, 2021). "MiR-34a acts as a tumor suppressor miR by down-regulating its target genes such as BCL-2 and SIRT1 and Notch1, Wnt/β-catenin signaling pathway, fra-1 and MYC." (PMID 34199293, 2021). "Further, A485 inhibited tumor growth in castration-resistant PCa xenograft models; it also led to a decrease in the mRNA levels of MYC and the AR-dependent gene SLC45A3, and a reduction in MYC protein levels." (PMID 33803759, 2021). "Application of GSEA showed that within each of PCS1, PCS2 and PCS3, HER2+ tumors were enriched for, e.g., MYC targets, and mTOR signaling in comparison to HER2− tumors, providing further evidence that HER2 status and BCCS provide independent information on tumor biology." (PMID 34642313, 2021).
tumor (continued). "Similarly, N-MYC downstream-regulated gene 2 (NDRG2), a well-known tumor suppressor, inhibits glycolysis in CRC cells by modulating c-MYC expression." (PMID 34887764, 2021). "MYC is a transcription factor in the nuclei that modulates cell growth and development, and regulates immune response in an antitumor direction by mediating programmed death ligand 1 (PD-L1) and promoting CRC tumor recurrence after adjuvant chemotherapy." (PMID 34440739, 2021). "The inhibition of LDHA in vivo led to reduced growth of MYC-driven tumours but not MYC-independent tumours." (PMID 34445233, 2021). "Breast cancer is pathologically demarcated by a plethora of abnormal gene profiles and transcripts that drive tumor initiation (MYC, Erb-B2 Receptor tyrosine kinase 2 (ERBB2), tumor progression (FOS, JUNB), proliferation and metastasis (epidermal growth factor receptor (EGRF))." (PMID 34299315, 2021). "Although our data is suggestive of a broad tumor suppressive role of MGA and PRC1.6 via antagonizing transcription of MYC and E2F targets, further studies will be required to elucidate the functional relevance of individual MGA-PRC1.6 targets such as STAG3 in tumorigenesis." (PMID 34236315, 2021). "A number of tumor-related pathways including the G2/M checkpoint, Mitotic spindle, DNA repair, PI3K-AKT-mTOR signaling pathway and MYC targets were differentially concentrated in the Linc00665 high expression phenotype." (PMID 33738251, 2021). "Therefore, in the case of the PE/CA-PJ49 tumor line, combined treatment with CisPt + RSV (p < 0.02, *) amplified the effect induced by CisPt, and it resulted in the reduction of c-MYC expression compared to the effect induced by RSV." (PMID 34204834, 2021). "Based on the observed synergy between BRAF and MYC, we surmise that distinct MYC targets may enhance KRAS-induced tumor growth via reversible immune suppression." (PMID 33674596, 2021). "Our results implied that the m6A-C1 was classified through multiple tumor-related biological processes (angiogenesis, EMT and hypoxia) and biomarkers (MYC and E2F); m6A-C2 was classified through several pathways correlated with tumorigenesis and progression, such as Wnt, TGF-beta and Notch pathways." (PMID 34650549, 2021). "In an oncogene MYC-induced HCC model, researchers specifically established liver-specific deletion of NF-κB essential modulator (NEMO) mice and found that NEMO deletion accelerated tumor progression and shortened survival." (PMID 34660326, 2021). "Reduction of the cellular material for the PCR validation also may well have reduced the repeatability of the tumor marker PCR assay and prevented validation of our LAMP assay for TERC/GAPDH and MYC GAPDH." (PMID 34790573, 2021). "In a study aimed at understanding the contribution of MYC to malignant transformation, lentiviral MYC was transduced into unsorted mouse cerebellum cells, which were subsequently orthotopically transplanted into NOD SCID gamma (NSG) mice, leading to tumour formation." (PMID 34445233, 2021). "H19, a direct transcriptional target of MYC, was shown to be up‐regulated in NSCLC tumour tissues." (PMID 33237626, 2021). "Furthermore, phosphorylation of the transcription factors MYC and JUN by DYRK2 is required for their degradation in the G1/S transition of the cell cycle, an event which is also tumor progression relevant." (PMID 33937075, 2021). "Furthermore, increases in the properties of stem cells were measured by assessing the capacity for tumor formation and performing transcriptional analysis of the OSKM genes (OCT4, SOX2, KLF4 and MYC), NANOG, NES and PROM1." (PMID 34364391, 2021).